GAST (gastrin)
Diseases named in the same sentence as GAST in open-access papers (continued):
Sharing a sentence is not in itself a finding about the gene and the disease.
colorectal cancer (continued). "We have evaluated the relationship between gastrin expression and the pattern of macrophage infiltration in samples from colorectal cancer and the influence of these peptides on the phenotype of macrophages differentiated from human peripheral monocytes in vitro." (PMID 24901518, 2014). "In addition, there seems to be a genetic bridge between hypergastrinemia and colorectal cancer, as gastrin expression is induced by the k-ras oncogene." (PMID 22719803, 2012). "While further studies are necessary to clarify any possible functional relationship, the present results do imply that a COX-2 mediated pathway may be stimulated by gastrin and may contribute to its trophic effects on colorectal cancer." (PMID 12189559, 2002). "However, in terms of gastrin level, although a significant difference was detected between the two groups, the multivariable analysis showed it didn’t have a strongest influence on the formation of colorectal cancer." (PMID 32704260, 2020). "Focusing in a more molecular basis, recent studies have proven that gastrin is related to upregulation of expression of inflammatory mediators, such as COX-2 and IL-8, whose inhibition can contribute in the prevention of colorectal cancer development." (PMID 22719803, 2012). "Our study did not reveal statistically significant differences in gastrin levels among colorectal cancer patients and controls." (PMID 22719803, 2012). "The significance of gastrin and H. pylori infection in colorectal cancer progress still appears like a never-ending conquest." (PMID 22719803, 2012). "Based upon these recent data, it is not surprising that gastrin precursors and not gastrin itself may be involved in colorectal cancer, bridging the gap regarding the presence of hypergastrinemia in colorectal cancer patients." (PMID 22719803, 2012). "Similarly, no statistical significance was found when the TNM stage of colorectal cancer was correlated to serum gastrin levels." (PMID 22719803, 2012). "Furthermore, the mean gastrin levels were not significantly higher in patients with colorectal cancer and H. pylori infection (mean value: 51 pg/mL), compared with the negative for infection colorectal cancer patients (mean value: 51.6 pg/mL) and the control group (P = n.s.)." (PMID 22719803, 2012).
autoimmune gastritis (20 papers, 2016 to 2025). Inflammation of the body fundic mucosa of the stomach. "Some study also indicate that gastrin level is an important marker for predicting the polyp risk in autoimmune gastritis patients." (PMID 39720008, 2024). "A preceding study has established the diagnostic significance of gastrin levels surpassing 355 pg/mL in the identification of autoimmune gastritis." (PMID 37504250, 2023). "While the link between vitamin B12 deficiency and fatigue remains nonspecific, the decision to test and subsequently supplement was guided by both clinical context and supportive biochemical findings, including elevated gastrin levels suggestive of underlying autoimmune gastritis." (PMID 40416105, 2025). "Following the exclusion of infectious, colorectal, and gynecologic malignancies, endoscopic and histological findings, in conjunction with elevated gastrin levels, confirmed the diagnosis of type 1 G-NET associated with autoimmune gastritis." (PMID 40673288, 2025). "Further, elevated serum gastrin levels, decreased pepsinogen levels, the presence of antiparietal cell antibodies, and consistent pathological findings confirmed autoimmune gastritis (AIG)." (PMID 40070929, 2025). "On the contrary, serum gastrin, which is synthesized by antral G cells, is often high in patients with autoimmune gastritis as a consequence of the hypo-achlorhydria due to the atrophy of the oxyntic mucosa." (PMID 38610988, 2024). "In autoimmune gastritis, reduction in gastric acid secretion triggers a compensatory response in the body, resulting in an increase in gastrin levels, a hormone that stimulates the release of gastric acid from parietal cells." (PMID 37504250, 2023). "Since gastrin is involved in carcinogenesis due to autoimmune gastritis and long-term profound acid inhibition, the use of netazepide is also a rational approach in these conditions." (PMID 37941554, 2023). "The findings in autoimmune gastritis suggest that WS is related to parietal cell degeneration and high serum gastrin levels, which are common conditions." (PMID 34203619, 2021). "The difference in prevalence of gastric NETs in patients with H. pylori gastritis versus autoimmune gastritis is most likely due to the difference in blood gastrin levels." (PMID 34207192, 2021). "Gastrin plays a central role in their pathogenesis since hypergastrinemia secondary to autoimmune gastritis with hypoacidity and gastrinoma with hyperacidity predispose to these tumours." (PMID 31108898, 2019). "Since autoimmune gastritis is usually asymptomatic, annual determinations of blood morphology, ferritin, vitamin B12, and gastrin levels are recommended in patients with APCA." (PMID 27525273, 2016). "The diagnosis of autoimmune gastritis typically involves endoscopic findings (e.g., atrophy of the gastric body mucosa), histopathological findings, autoantibodies against parietal cells and intrinsic factors, and serum gastrin levels." (PMID 39246633, 2024). "Diagnosis of autoimmune gastritis still relies on the pathological examination of gastric body biopsies taken from the body mucosa, and it can be reinforced by non-invasive serological biomarkers such as gastrin, APCA, and pepsinogens." (PMID 39632655, 2024). "Measuring gastrin levels can aid in the diagnosis and monitoring of autoimmune gastritis." (PMID 37504250, 2023). "It is believed that elevated gastrin levels contribute to inflammation in autoimmune gastritis, leading to the development of adenocarcinoma and gastric neuroendocrine tumor I. However, in our study, we examined the serum gastrin levels at the time of resection of gastric epithelial neoplasms." (PMID 37835553, 2023). "In those with established oxyntic atrophy either due to H. pylori or autoimmune gastritis, treatment with the specific gastrin antagonist netazepide could be an option." (PMID 34207192, 2021).
autoimmune gastritis (continued). "Both Helicobacter pylori infection and PPIs treatment alone or in combination may induce a degree of hypergastrinemia that in the long-term is sufficient to evoke gastric tumors based upon the gastrin values in patients with autoimmune gastritis and gastric NETs (carcinoids)." (PMID 32796591, 2020). "Similarly, young patients with autoimmune gastritis may be treated with gastrin antagonist." (PMID 32796591, 2020). "Laboratory diagnosis of autoimmune gastritis is based on determination of serum biomarkers, for example, anti-parietal cell autoantibodies (APCA) and antibodies directed against an inner factor, and in the case of atrophic gastritis, on determination of the concentration of pepsinogen and gastrin." (PMID 27525273, 2016).
gastric adenocarcinoma (18 papers, 1992 to 2025). "The risk of gastric adenocarcinoma was compared between participants with prediagnostic hypergastrinemia (>60 pmol/L) and normal serum gastrin (≤60 pmol/L)." (PMID 33091962, 2021). "Gastrin promotes the proliferation and inhibits the apoptosis of gastric adenocarcinoma cells primarily through binding to CCK2R." (PMID 41210850, 2025). "This is the first study that demonstrates a marked association between hypergastrinemia and subsequent development of gastric adenocarcinoma in the gastrin‐responsive, proximal stomach in a larger general population." (PMID 33091962, 2021). "It has been reported that gastrin peptide and its receptors can be expressed in human gastric adenocarcinoma." (PMID 33936196, 2021). "Gastrin, a peptide hormone, is synthesized in the G cells of the antrum; however, gastrin expression also is found in many gastric adenocarcinomas of the stomach corpus." (PMID 29866191, 2018). "We show that the gastrin induced migration and survival of gastric adenocarcinoma cells is partially dependent on induced autophagy." (PMID 28109268, 2017). "Collectively, the data demonstrates that the gastric adenocarcinoma cell lines display an increased autophagy in response to gastrin in a CCKBR dependent manner." (PMID 28109268, 2017). "This study explores the role of autophagy in response to gastrin in gastric adenocarcinoma cell lines." (PMID 28109268, 2017). "In this study, we find that gastrin treatment induces autophagy in the gastric adenocarcinoma cell lines AGS-Gr and MNK45, concomitant with the activation of the STK11-PRKAA2-ULK1 signaling cascade." (PMID 28109268, 2017). "We find that the peptide hormone gastrin induces autophagy in two gastric adenocarcinoma cell lines via the STK11-PRKAA2-ULK1 pathway." (PMID 28109268, 2017). "In the present study we show that gastrin induces transient SIK1 expression in pancreatic and gastric adenocarcinoma cells, and that the gastrin-induced SIK1 expression is negatively regulated by Inducible cAMP early repressor (ICER)." (PMID 25384047, 2014). "Evidence provided here demonstrates that SIK1 is regulated by gastrin and influences gastrin elicited signalling in gastric adenocarcinoma cells." (PMID 25384047, 2014). "We further examined the role of NR4A2 in gastrin induced responses by employing the gastric adenocarcinoma cell line AGS-GR Gastrin induced a ~8-fold induction of NR4A2 mRNA in AGS-GR cells, followed by a rapid decrease to baseline after ~4 h of stimulation." (PMID 24086717, 2013). "Consistent with our current findings, we have previously reported that gastrin enhanced cyclin D1 protein and cyclin D1 promoter activity in the human gastric adenocarcinoma cell line AGS-B." (PMID 15798764, 2005). "This suggests that gastrin may inhibit the occurrence and progression of MNU-induced gastrin-dependent gastric adenocarcinoma, which is associated with its regulation of trefoil factor 1 gene silencing and associated epigenetic changes." (PMID 40673273, 2025). "This supports the hypothesis that hypergastrinemia mediates development of gastric adenocarcinoma in the proximal stomach, where mucosal proliferation is stimulated by gastrin." (PMID 33091962, 2021). "The finding supports the hypothesis that hypergastrinemia mediates the development of gastric adenocarcinoma in the proximal stomach, where mucosal proliferation is stimulated by gastrin." (PMID 33091962, 2021). "On the other hand, hypergastrinemia in insulin-gastrin (InsGas) transgenic mice causes gastric adenocarcinoma which is not accompanied by hyperplasia of ECL cells." (PMID 28980157, 2018). "Cisplatin is used in the treatment of gastric adenocarcinomas, and we tested whether gastrin induced autophagy could modify the cellular response to cisplatin in vitro." (PMID 28109268, 2017). "Thus it was of interest to examine whether NR4A2 would influence gastrin induced migration and invasion in our gastric adenocarcinoma cells." (PMID 24086717, 2013).
gastric adenocarcinoma (continued). "We demonstrate that gastrin increases the expression of the autophagy markers MAP1LC3B-II and SQSTM1 in gastric adenocarcinoma cells." (PMID 28109268, 2017). "Although a substantial part of the gastric adenocarcinomas express gastrin and CCKBR, the role of gastrin in tumor development is not completely understood." (PMID 28109268, 2017). "We show that SIK1 knockdown by siRNA brings along higher migratory activity in gastric adenocarcinoma cells, indicating that SIK1 suppresses gastrin-mediated migration." (PMID 25384047, 2014). "We conclude that gastrin induced NR4A2 expression and transactivation play an important role in gastric adenocarcinoma cells." (PMID 24086717, 2013). "In vivo, NR4A2 is strongly expressed in the gastrin responsive neuroendocrine ECL cells in normal mucosa, whereas gastric adenocarcinoma tissue reveals a more diffuse and variable expression in tumor cells." (PMID 24086717, 2013). "Our principal findings are that gastrin regulates NR4A2 expression and activity in gastric adenocarcinoma AGS-GR cells." (PMID 24086717, 2013). "Gastrin over-expressed in an insulin-gastrin transgenic mouse model (INSGAS) induces corpus atrophy in those mice, spontaneously progressing to gastric adenocarcinoma with advanced age." (PMID 19270747, 2009). "To investigate whether gastrin directly affects PAPPA2 expression in CCK2R-expressing gastric epithelial cells, we used human gastric adenocarcinoma cells that have been stably transfected with the human CCK2 receptor (AGSGR)." (PMID 32004755, 2020). "Collectively, this suggests a role of SIK1 in gastrin induced responses and suggest that SIK1 may act as tumour suppressor in gastric adenocarcinoma cells." (PMID 25384047, 2014). "In accordance with this, we also observed changed NR4A2 expression in gastric adenocarcinomas, seemingly being dominated by a general expression in tumor cells compared to the mainly strong NR4A2 expression in the gastrin responsive neuroendocrine ECL cells in normal mucosa." (PMID 24086717, 2013). "Gastrin but not CCK promotes growth of human gastric adenocarcinoma cells." (PMID 32210918, 2020). "However, the role of gastrin in the progression of gastric adenocarcinoma is not completely understood." (PMID 28109268, 2017).
diabetes (17 papers, 2014 to 2025). "Although the presence of GAST+ cells in human T2D islets was recognized earlier, the relevance to diabetes pathogenesis and mechanism was unclear." (PMID 37606041, 2023). "So far, modified CCK and gastrin peptides are being examined as potential drugs for therapy of type 1 as well as type 2 diabetes mellitus." (PMID 31853211, 2019). "An association between gastrin/CCK peptides and islet-cell functions (and hence a role for these peptides in diabetes therapy) has been discussed and examined in the last decades." (PMID 31853211, 2019). "In previous studies, co-treatment with EGF and gastrin induced beta cell regeneration and normalized glycemia in rodent models of chemically induced diabetes and in NOD mouse model." (PMID 26452142, 2015). "There were not significant differences in the positive rate of Ig G and Cag A and family history between the two groups (p>0.05), but there were significant differences in gastrin level, obesity, smoking history, alcohol consumption and diabetes mellitus between the two groups (p<0.05)." (PMID 32704260, 2020). "Thus, an alteration in the H+/somatostatin (SST) pathway, which is involved in thyroid regulation and gastrin and insulin secretion, may trigger not only achlorhydria but also hypothyroidism and diabetes." (PMID 34944008, 2021). "Ga = gastrin, Glu = glucagon, In = insulin, PP = polypeptide, SS = somatostatin, VIP = vasoactive intestinal peptide, DM = diabetes mellitus, RFA = radiofrequency ablation." (PMID 34118524, 2021).
gastric ulcer (17 papers, 2011 to 2026). An ulcerated lesion in the mucosal surface of the stomach. "Ethanol-induced gastric ulceration was associated with a significant elevation in serum gastrin and somatotropin levels relative to control rats (p < 0.0001 for both hormones)." (PMID 40867886, 2025). "Alcohol, on the other hand, predisposes to gastric ulceration, stimulates gastric acid secretion as well as enhancing gastrin release." (PMID 33897215, 2020). "On one hand this finding is of interest, because it is believed that high gastrin levels might cause gastric ulcers, affecting the welfare of sled dogs." (PMID 34765666, 2021). "The excess of gastrin has been related with the appearance of gastric ulcers in humans because this hormone induces the release of hydrochloric acid (HCl) by the parietal gastric cells." (PMID 36496782, 2022). "But, it expressed a significant reduction in histamine and gastrin contents to 44.27% and 41.17%, respectively, in comparison to the gastric ulcer control group." (PMID 31731465, 2019). "But it significantly decreased histamine and gastrin contents in comparison to the gastric ulcer control group." (PMID 31731465, 2019). "But, it expressed a significant reduction in histamine and gastrin contents to 50.49% and 46.85%, respectively, in comparison to the gastric ulcer control group." (PMID 31731465, 2019). "But, it expressed a significant reduction in histamine and gastrin contents to 24% and 23.5%, respectively, in comparison to the gastric ulcer control group." (PMID 31731465, 2019). "Furthermore, epithelial regeneration in gastric ulcer disease is initiated by gastrin release, demonstrating the importance of G‐cells in this context." (PMID 35899973, 2022). "In addition, omeprazole significantly decreased gastrin content in comparison to the gastric ulcer control group." (PMID 31731465, 2019). "Additionally, gastric ulcer control rats showed a significant increase in gastrin content in comparison to normal control rats." (PMID 31731465, 2019). "However, the interpretation of these observations is complicated by the fact that a significant proportion of gastric ulcer patients have elevated circulating gastrin concentrations (particularly G-34), and most are H. pylori positive." (PMID 23494120, 2013). "Ethanol is well known to induce gastric ulcers via multi-factorial mechanisms such as the impairment of gastric defensive factors like mucus dissolution or by increasing offensive factors such as acid secretion or gastrin release." (PMID 24363683, 2011). "Gastric hyperacidity and hypergastrinemia are purported to cause gastric ulceration in dogs with chronic kidney disease (CKD); however, no published studies have evaluated gastric pH with serum gastrin concentrations in dogs with CKD." (PMID 37874019, 2023).